FTO (FTO alpha-ketoglutarate dependent dioxygenase)
Diseases named in the same sentence as FTO in open-access papers (continued):
Sharing a sentence is not in itself a finding about the gene and the disease.
liver fibrosis (3 papers, 2014 to 2025). "Our findings provide new insight showing that targeting the FTO/ULK1 axis may be a promising strategy for clinical anti-liver fibrosis therapy." (PMID 39175431, 2024). "In this study, we find that the m6A demethylase fat mass and obesity-associated protein (FTO), which is the m6A methylase with the most significant difference in expression, is upregulated during HSC activation and bile duct ligation (BDL)-induced hepatic fibrosis." (PMID 39175431, 2024). "In this study, we revealed that compared with other methylases, FTO, which is the m6A methylase with the most significant difference in expression, was upregulated during HSC activation and BDL-induced hepatic fibrosis." (PMID 39175431, 2024). "We found that the m6A demethylase FTO promoted autophagy by recognizing theULK1 m6A binding site, thus triggering HSC activation and eventually leading to liver fibrosis." (PMID 39175431, 2024). "In summary, this study demonstrated that the m6A demethylase FTO promotes HSC autophagy by targeting ULK1, resulting in HSC activation and ultimately leading to hepatic fibrosis." (PMID 39175431, 2024). "Importantly, our study first revealed that FTO overexpression aggravated HSC activation and hepatic fibrosis, whereasFTO knockdown markedly inhibited HSC activation and hepatic fibrosis." (PMID 39175431, 2024). "Importantly, we identify that FTO overexpression aggravates HSC activation and hepatic fibrosis via autophagy." (PMID 39175431, 2024). "In addition, the region with upregulated FTO was highly coincident with HSC regions, indicating that the increase in FTO is responsible for HSC activation and cholestatic hepatic fibrosis." (PMID 39175431, 2024).
lupus (3 papers, 2020 to 2025). "The first available data were focused on the mRNA expression of m6A writers (METTL3, METTL14, and WTAP), erasers (FTO and ALKBH5) and readers (YTHDF2) in peripheral blood mononuclear cells (PBMCs) from lupus affected patients." (PMID 33807762, 2021).
myelodysplastic syndrome (3 papers, 2022 to 2025). A clonal hematopoietic disorder characterized by dysplasia and ineffective hematopoiesis in one or more of the hematopoietic cell lines. "This striking finding paves the way to improve the therapeutic effect of AML or myelodysplastic syndromes (MDS) in combination with FTO inhibitors or anti-LILRB4 monoantibody based on HMAs." (PMID 35720276, 2022).
myocardial inflammation (3 papers, 2022 to 2025). "FTO was underexpressed in LPS‐induced cardiomyoblasts, and its decreased expression might be related to endotoxemia‐induced myocardial inflammation and dysfunction." (PMID 39739936, 2025).
non-alcoholic steatohepatitis (3 papers, 2021 to 2023). "FTO expression increased in the fatty liver of rats and patients with nonalcoholic steatohepatitis." (PMID 36352530, 2023). "In addition, the present study demonstrated that FTO expression level is higher in the liver of patients with non-alcoholic steatohepatitis." (PMID 34017338, 2021). "In our study, we observed an increase of FTO in the fatty liver of HFD mice, consistent with previous findings in the fatty liver of rats and patients with nonalcoholic steatohepatitis, and a corresponding decrease in m6A methylation." (PMID 36352530, 2023).
oral cancer (3 papers, 2021 to 2023). "FTO upregulation in arecoline-exposed oral cancer enhanced PD-L1 transcript levels and stability through m6A modification and MYC activity." (PMID 36859310, 2023). "Elucidating the biological function role of FTO in arecoline‐promoted oral cancer progression is urgently needed." (PMID 34378866, 2021). "Forcing FOXA2 expression inhibited, whereas silencing FOXA2 expression promoted FTO expression in oral cancer cells, proving that FTO is negatively regulated by FOXA2." (PMID 34378866, 2021). "Our data suggested that FTO not only plays an oncogenic role in oral cancer development, but also plays a pivotal role in arecoline‐induced tumorigenesis of oral cancer." (PMID 34378866, 2021). "The immune-inhibitory role of FTO has also been confirmed in oral cancer." (PMID 36859310, 2023). "Indeed, we demonstrated that depletion of FTO significantly reduced arecoline‐transformed oral cancer cell proliferation, migration, stemness, and cisplatin‐resistance in vitro, as well as tumor growth in vivo." (PMID 34378866, 2021). "However, the biological function role of FTO in arecoline‐induced oral cancer is largely unknown." (PMID 34378866, 2021).
pancreatic ductal adenocarcinoma (3 papers, 2021 to 2025). An infiltrating adenocarcinoma that arises from the epithelial cells of the pancreas. "This study analyzed eight m6A regulators (METTL3, METTL14, WTAP, FTO, ALKBH5, and YTHDF1-3) in pancreatic ductal adenocarcinoma (PDAC) and found that only RNA m6A demethylase ALKBH5 serves as an independent favorable prognostic marker for this tumor." (PMID 34733841, 2021).
pancreatic neuroendocrine tumor (3 papers, 2025). Pancreatic endocrine tumor, also known as pancreatic neuroendocrine tumor (PNET), describes a group of endocrine tumors originating in the pancreas that are usually indolent and benign, but may have the potential to be malignant. "In contrast, in pancreatic neuroendocrine tumors, FTO promotes malignancy by enhancing APOE expression through FASN‐mediated lipid metabolism, suggesting an oncogenic role." (PMID 41141648, 2025). "FTO-induced APOE activates the PI3K/AKT/mTOR signaling pathway by regulating the ubiquitination state of FASN, which enhances lipid metabolism and proliferative capacity, thereby promoting the malignant progression of pancreatic neuroendocrine tumors." (PMID 40764609, 2025).
peripheral nerve injury (3 papers, 2020 to 2022). Injury to a peripheral nerve. "After peripheral nerve injury, FTO in DRG is involved in the generation and maintenance of hyperalgesia in mice and participates in hemorrhage-induced thalamic pain." (PMID 35634463, 2022). "After peripheral nerve injury, the binding of FTO to MMP-9 mRNA decreased and the enrichment of m6A on MMP-9 mRNA increased." (PMID 35634463, 2022). "After peripheral nerve injury, Runx1 may be responsible for the loss of the m6A site in the EHMT2 mRNA encoding G9a through binding to FTO gene promoter and increasing the FTO gene expression in the injured DRG." (PMID 36466810, 2022).
sarcoma (3 papers, 2022 to 2024). A usually aggressive malignant neoplasm of the soft tissue or bone. "As GEPIA and TCGA database indicates, FTO is upregulated in various tumors, including sarcoma (SARC)." (PMID 39449798, 2024). "m6A is removed by demethylases such as FTO and ALKBH5, whose expression levels were significantly correlated with those of KCNH2 in PRAD, sarcoma (SARC), PAAD, and TGCT." (PMID 36792990, 2023).
acromegaly (2 papers, 2018 to 2022). Acromegaly is an acquired disorder related to excessive production of growth hormone (GH) and characterized by progressive somatic disfigurement (mainly involving the face and extremities) and systemic manifestations. "Identification of two single nucleotide polymorphisms of FTO gene was carried out in 51 patients with acromegaly using the minisequencing method." (PMID 28913579, 2018). "Aim of this study was to investigate the allele frequencies of two FTO gene polymorphisms: rs9939609 and rs9930506 in patients with acromegaly and to examine the association of FTO gene polymorphisms with BMI and selected metabolic parameters." (PMID 28913579, 2018). "The aim of this study was therefore to investigate the risk allele frequencies of two FTO gene polymorphisms: rs9939609 and rs9930506 in patients with acromegaly and to examine the association of FTO gene polymorphisms with BMI and selected metabolic parameters." (PMID 28913579, 2018). "There is an association between FTO gene polymorphisms and HDL cholesterol concentration, suggesting FTO gene polymorphisms may be associated with higher CVD risk in patients with acromegaly." (PMID 28913579, 2018). "Consistently, carriers of homozygotes for the risk allele of FTO were found to have 1.25-fold lower HDL cholesterol concentration than carriers of the non-risk genotype in patients with acromegaly." (PMID 36185685, 2022).
acute lymphoblastic leukemia (2 papers, 2023 to 2025). Leukemia with an acute onset, characterized by the presence of lymphoblasts in the bone marrow and the peripheral blood. "Using T cell acute lymphoblastic leukemia (T-ALL) as a model system, we identify FTO as a unique vulnerability in T cell leukemia." (PMID 40435251, 2025). "Finally, the mechanism that we propose for the activation of IRX3 in AML cannot explain how this transcription factor gene is so highly expressed in around 50% of cases of T-acute lymphoblastic leukemia, where expression of FTO-lncAML is not observed." (PMID 37539037, 2023).
adenoma (2 papers, 2021 to 2022). A neoplasm arising from the epithelium. "FTO expression is strictly nuclear in healthy adjacent tissue as well as in precursor lesions of CRC (adenoma)." (PMID 33741917, 2021). "M6A modification is regulated by RNA methyltransferase and demethylase, hence we assessed the expression of methyltransferase (METTL3, METTL14 and WTAP) and demethylase (FTO and ALKBH5) in both adenoma and CRC." (PMID 35012593, 2022). "Next, we evaluated FTO expression and localization in tumor microarrays (TMA) from different colorectal stages: adenoma, 1, 2, 3, 4, and metastases (n = 52)." (PMID 33741917, 2021). "Relative to the normal group, FTO was significantly lower in the adenoma group but not in the CRC group." (PMID 35012593, 2022).
androgen excess (2 papers, 2013 to 2019). "Similar results for SNPs in the FTO gene have been reported in a previous metformin pharmacogenetic study for the BMI Z-score change in girls with androgen excess." (PMID 31527397, 2019).
asthenospermia (2 papers, 2016 to 2021). "It has been reported that the downregulation of FTO mediates the development of male asthenospermia through m6A modifications." (PMID 34315853, 2021).
atrial fibrillation (2 papers, 2024). A disorder characterized by an electrocardiographic finding of a supraventricular arrhythmia characterized by the replacement of consistent P waves by rapid oscillations or fibrillatory waves that vary in size, shape and timing and are accompanied by an irregular ventricular response. "Correlation analysis of gene expression of APOE, FTO, and LPL genes with the clinical parameters of atrial fibrillation in studied groups." (PMID 39166676, 2024).
bipolar disorder (2 papers, 2019 to 2024). A disorder of the brain that causes unusual shifts in mood, energy, activity levels and the ability to carry out day-to-day tasks. "The present work found an association of FTO variants with bipolar disorder." (PMID 31033179, 2019). "One of the limitations of the present work is that patients analyzed were not drug‐naïve which could be a confounding factor in this population; nevertheless, this work reports an association of FTO variants with bipolar disorder." (PMID 31033179, 2019).
Cachexia (2 papers, 2013 to 2017). Severe weight loss, wasting of muscle, loss of appetite, and general debility related to a chronic disease. "An initial study in chronic obstructive pulmonary disease (COPD) suggests variation of lung function with FTO genotype and proposes a link with cachexia in a subset of these patients." (PMID 23300482, 2013).
cerebral infarction (2 papers, 2024 to 2026). An ischemic condition of the brain, producing a persistent focal neurological deficit in the area of distribution of the cerebral arteries. "Our experiments unveiled reduced Fe2+ and 4HNE contents and enhanced GPX4 levels after overexpressing FTO in cerebral I/R models, along with reduced cerebral infarction and edema, and improved mitochondrial functions, as well as enhanced cell viability and weakened cell apoptosis in OGD/R neurons." (PMID 38430221, 2024).
chronic kidney disease (2 papers, 2016 to 2023). Impairment of the renal function secondary to chronic kidney damage persisting for three or more months. "The FTO rs17817449 variants are associated with increased risks of chronic kidney diseases (CKD) and onset of ESRD21." (PMID 26727661, 2016). "These FTO variants are also associated with end stage renal disease and all-cause mortality in chronic kidney diseases." (PMID 26727661, 2016). "Previous case-control clinical studies have suggested the associations between FTO polymorphism and risks of end-stage renal disease (ESRD)." (PMID 26727661, 2016). "Our data provide a mechanistical insight into the association of FTO and chronic kidney diseases." (PMID 26727661, 2016).
cocaine addiction (2 papers, 2020 to 2025). "This suggests that FTO may play a key role in the regulation of cocaine addiction." (PMID 40590504, 2025). "Indeed, DBS could inhibit cocaine addiction by directly modulating the dopaminergic signaling pathway rather than relying on FTO or DAT." (PMID 33343932, 2020).
colitis (2 papers, 2021 to 2025). Inflammation of the colon. "m6A has been reported its potential connections with IBD, METTL3 and METTL14 deficiency in immune cell induce colitis; m6A eraser FTO protects IBD patients from adverse reactions after thiopurine treatment." (PMID 35127705, 2021).
colorectal adenoma (2 papers, 2023 to 2025). An adenoma that arises from the colon or rectum. "In a study conducted on an African-American cohort, the FTO SNPs rs17817449 and rs8050136 were associated with colorectal adenomas." (PMID 40361322, 2025).
deafness (2 papers, 2020 to 2023). An inherited or acquired condition characterized by the complete loss of the ability to hear from one or both ears. "Some of them (e.g., ARID5B, CTBP2, and FTO) were previously identified as causal loci of Mendelian forms of deafness." (PMID 37165447, 2023).
diabetic cardiomyopathy (2 papers, 2022 to 2025). Diabetic cardiomyopathy is a disorder of the heart muscle in people with diabetes. "Potentially, through inhibition of cardiac fibrosis and cardiomyocyte hypertrophy, overexpressions of FTO could lead to cardiac functional benefits in diabetic cardiomyopathy mice." (PMID 41007655, 2025). "While FTO knockout in a model of pressure-overload-induced HFrEF decreases contractility and increases ventricular dilatation, its overexpression in a model of diabetic cardiomyopathy has been shown to inhibit fibrosis and hypertrophy." (PMID 35991314, 2022). "Hence, the therapeutic role of FTO in diabetic cardiomyopathy, perhaps via regulation of GLUT4 expression, warrants targeted attention." (PMID 35991314, 2022).
gastric adenocarcinoma (2 papers, 2024 to 2025). "While the transcriptome data from the TCGA data portal and GTEx database showed that the level of FTO mRNA was significantly higher in stomach adenocarcinoma (STAD) samples than adjacent normal tissues (ANT)." (PMID 38556586, 2024). "Our findings indicate that FTO overexpression does not enhance cellular migration in HCC1937 cells, unlike in Panc-1, SW1990, or gastric adenocarcinoma cell lines, as previously reported." (PMID 40572597, 2025).
gastric tumors (2 papers, 2023 to 2025). "To further verify the role of FTO in GC development, we generated Fto conditional knockout (Fto-cKO) and wild-type (WT) mice and induced gastric tumors using N-methyl-N-nitrosourea (MNU)." (PMID 39773744, 2025).
hepatoblastoma (2 papers, 2021 to 2023). Hepatoblastoma (HB) is a malignant hepatic tumor and is the most common pediatric liver cancer. "Our group has previously reported that many genetic variants of genes encoding RNA m6A and m7G methyltransferase, demethylase, and m6A-reading proteins confer hepatoblastoma susceptibility, including METTL3, METTL4, AlkB homolog 5 (ALKBH5), FTO, YTHDC1, YTHDF1, WTAP, WDR4, and METTL1." (PMID 37531210, 2023).
Miscarriage (2 papers, 2022 to 2024). A pregnancy that ends at a stage in which the fetus is incapable of surviving on its own, defined as the spontaneous loss of a fetus before the 22th week of pregnancy. "In addition, FTO as an RNA demethylase could affect the expression of genes involved in placental function and fetal development through epigenetic mechanisms leading to an increased risk of spontaneous abortion." (PMID 39758312, 2024).
myeloid leukemia (2 papers, 2020 to 2021). A clonal proliferation of myeloid cells and their precursors in the bone marrow, peripheral blood, and spleen. "More particularly, FTO inhibitors, meclofenamic acid (MA), or its ethyl ester form (MA2) have been recently identified as specific FTO inhibitors that have shown antitumor activity on myeloid leukemia (AML) and GBM, prostate, and uterine cervical cancers." (PMID 33375621, 2020).
neuropathic pain (2 papers, 2021 to 2023). Chronic pain caused by damage to nerve fibers. "The function of m6A modification in DRGs has recently gained attention, with one study demonstrating that the increased expression of RNA m6A demethylase FTO contributes to spinal nerve ligation-induced neuropathic pain in mice." (PMID 37535403, 2023).
nicotine dependence (2 papers, 2019 to 2022). Physical and psychological dependence on nicotine. "FTO and LINGO2 have suggestive associations with nicotine dependence." (PMID 35613103, 2022).
Osteopenia (2 papers, 2019 to 2022). Osteopenia is a term to define bone density that is not normal but also not as low as osteoporosis. "Aging and osteopenia were associated with a decline in m6A content in total RNA, which was consistent with the up-regulation of FTO expression." (PMID 31998240, 2019). "FTO is overexpressed in bone marrow and promotes BMSCs adipocyte differentiation and restrains osteoblast differentiation by GDF11–FTO–Pparg axis, thereby inhibiting bone formation and accelerating the development of osteopenia." (PMID 35735243, 2022). "FTO knockout repressed the development of osteopenia in vivo through upregulation of adipocytic and down-regulation of an osteoblastic gene." (PMID 31998240, 2019).
overnutrition (2 papers, 2011 to 2025). An imbalanced nutritional status resulting from excessive intake of nutrients. "The FTO gene is recognised for its role in regulating eating behaviour and appetite, is associated with a higher risk of overnutrition primarily due to increased food intake and preference for high-energy and high-fat foods." (PMID 40362863, 2025). "In this study we examined the impact of maternal obesity and early life overnutrition on FTO expression in the hypothalamus and liver_ENREF_18." (PMID 21980407, 2011). "Notably, among numerous metabolism-related genes, FTO was identified as the strongest predictor of polygenic overnutrition." (PMID 40362863, 2025). "Liver FTO (P = 0.049) and FAS (P = 0.037) mRNA expression was decreased by maternal overnutrition in both HN and HS groups." (PMID 21980407, 2011).
premature ovarian failure (2 papers, 2023 to 2024). "The SNP rs9941349, located within the FTO gene intron, has been associated with abnormalities in FTO and linked to impaired oocyte maturation and premature ovarian failure." (PMID 39024334, 2024). "Therefore, FTO is also required for folliculogenesis, and its deletion might lead to premature ovarian failure." (PMID 37146971, 2023).
pulmonary tuberculosis (2 papers, 2014 to 2022). A bacterial infection that affects the lungs and is caused by Mycobacterium tuberculosis. "The FTO polymorphism rs9939609 is associated with a risk of pulmonary tuberculosis in the Chinese population." (PMID 25377722, 2014). "To test this hypothesis, we performed a case-control study to assess the association of two common FTO polymorphisms (rs9939609 and rs8050136) with pulmonary tuberculosis in a Chinese population." (PMID 25377722, 2014). "The m6A methylation was involved in the pathogenesis of pulmonary tuberculosis (PTB), and our study aimed to reveal the potential association of m6A demethylase (ALKBH5, FTO) genes variation, expression levels and PTB." (PMID 36619747, 2022).